CD28 (CD28 molecule)
Diseases named in the same sentence as CD28 in open-access papers (continued):
Sharing a sentence is not in itself a finding about the gene and the disease.
Stroke (19 papers, 2014 to 2025). Sudden impairment of blood flow to a part of the brain due to occlusion or rupture of an artery to the brain. "High percentages of CD4+CD28- T cells have been associated with instable angina and the increased risk of relapse of an acute coronary event or stroke." (PMID 39456708, 2024). "In stroke, other Treg-modulating therapies, including CD28 superagonist, IL-33, IL-2/IL-2-antibody complex, and adoptive Treg cell transfer, have been shown to increase peripheral Treg frequencies by two- to three-fold in young mice." (PMID 33516262, 2021). "Another study found an increase in CD4+CD28 null lymphocyte cells in stroke survivors or those who died from ischemic stroke." (PMID 33922467, 2021). "We observed a significant relationship between CD28 null cells peripheral percentage and Scandinavian Stroke Scale and NIHSS scores." (PMID 25997053, 2015). "In T cells, CD8 on CD28+ CD45RA– CD8+ T cells (IVW: OR 1.09, 95% CI 1.02–1.17; p = 0.016) and herpes virus entry mediator (HVEM) on immature CD8+ T cells (IVW: OR 1.04, 95% CI 1.01–1.08; p = 0.009) were associated with increased stroke risk." (PMID 38323746, 2024). "Analysis of this study also showed that the percentage of CD+CD28 null lymphocyte cells may be useful for distinguishing between subtypes of stroke." (PMID 33922467, 2021). "It has been found that, during the acute phase of post-stroke neuroinflammation, CD4+ and CD28 null populations are more numerically represented and significantly predominate when the etiopathogenesis of stroke is cardioembolic compared to lacunar or LAAS subcategory." (PMID 33317034, 2020). "Also in murine cerebral ischemia, Treg amplification with a CD28 superagonistic monoclonal antibody or rapamycin treatment attenuated the neurological outcome after stroke induction." (PMID 31383034, 2019). "ROC curve analysis showed that CD28 null cell percentage may be useful to differentiate between stroke subtypes." (PMID 25997053, 2015). "While certain Treg phenotypes, such as CD28+ CD45RA+ CD8br %CD8br and Activated & resting Treg %CD4+, exhibit neuroprotective effects, others like CD127 on granulocyte, CD3 on CD39+ secreting Treg, CD4 on activated & secreting Treg, DN (CD4-CD8-) AC are associated with an elevated risk of stroke." (PMID 38894965, 2024). "This study revealed an association between the high probability of death after a stroke or new ischemic episodes and the CD4+CD28 null lymphocyte cell count, and proposed that the number of these lymphocytes could serve as a warning biomarker against recurrence of an ischemic event or death." (PMID 33922467, 2021). "Finally, at ROC curve analysis our findings showed that CD28 null cell peripheral percentage may be useful to differentiate between stroke subtypes." (PMID 25997053, 2015). "As the stroke represents a strong inflammatory event, we performed anti-CD3/anti-CD28 (αCD3/αCD28) treatment of all samples to imitate the inflammatory stimulus." (PMID 39372701, 2024). "In our study, we reported higher serum levels of IL-6 and TNF-α and higher percentage of peripheral CD4+ cells and CD4+CD28 null in subjects with acute ischemic stroke in comparison with subjects without stroke." (PMID 30995924, 2019). "First, we do not have any information about CD28 null peripheral percentage in baseline conditions prior of stroke occurrence." (PMID 25997053, 2015). "CD80/CD28 interactions played a prominent regulatory role for the CD8+ T-cells and the PD-1/PD-L2 interactions were dominant in controlling the CD4+ T-cell responses in WT mice, after stroke." (PMID 25157219, 2014). "As the CD28 SA had no impact on stroke volumes (control group: 30.4±2.8 mm3; CD28 SA group: 37.3±12.5 mm3, P>0.05) a direct effect of the CD28 SA on clinical outcome in the absence of T and B cells could be excluded." (PMID 25315859, 2015).
Stroke (continued). "Interestingly, the CD80/CD28 interactions appeared to play a prominent regulatory role for the CD8+ T-cells while the PD-1/PD-L2 interactions were dominant in controlling the CD4+ T-cell responses in WT mice, after stroke." (PMID 25157219, 2014). "Also, CD80/CD28 interactions played a prominent regulatory role for the CD8+ T-cells and the PD-1/PD-L2 interactions were dominant in controlling the CD4+ T-cell responses in WT mice after stroke." (PMID 25157219, 2014).
B-cell lymphoma (18 papers, 2013 to 2026). "Recently, the novel CD19CAR-T cells incorporated with B-cell costimulatory molecules of CD79A/CD40 demonstrated superior antitumor activity in the B-cell lymphoma model compared with CD28 or 4-1BB." (PMID 36505428, 2022). "Patients with B-cell lymphoma were found to have a dysregulated HSP response to CD3/CD28 stimulation." (PMID 36359267, 2022). "Parallel comparison of 4-1BB or CD28 co-stimulated CAR19-T cells for B-cell lymphoma suggests that 4-1BB is more beneficial and tolerated for the clinical performance." (PMID 34113336, 2021). "Axicabtagene ciloleucel was one kind of autologous anti-CD19 CAR-T cell which consisted of CD28 transmembrane domain and CD28 costimulatory domain for patients with B-cell lymphoma." (PMID 34256851, 2021). "Here we have assessed the expression of various HSP families, including cytosolic (HSP90α, HSP90β, HSP70, HSC70, and HSP40/DNAJB1), endoplasmic reticulum (GRP78), and mitochondrial (HSP60) HSP homologs in resting and CD3/CD28-stimulated T cells in healthy controls and B-cell lymphoma patients." (PMID 36359267, 2022). "We found that B-cell lymphoma (BCL) patients have dysregulated expression of intracellular and extracellular HSPs, immune checkpoints PD-1, CTLA-4, and STAT3 in CD3/CD28-activated T cells." (PMID 36359267, 2022). "Using biopsy specimens from patients with B-cell NHL, we observed that TGF-β profoundly inhibits the proliferation of both CD4+ and CD8+ T cells stimulated by anti-CD3 and CD28 Abs." (PMID 23555036, 2013). "For example, decitabine-primed tandem CD19/CD20 CAR-T cells treatment in relapsed/refractory B-cell NHL (r/r B-cell NHL) (NCT04697940), sequential low-dose decitabine with PD-1/CD28, CD19 CAR-T in relapsed/refractory B-cell lymphoma (r/r B-cell lymphoma) (NCT04850560)." (PMID 35463343, 2022). "Therefore, we co-incubated murine A20 B cell lymphoma cells that were uninfected or infected overnight with CPXV (Brighton Red (BR) strain) or VACV (MOI = 5) (Western Reserve) with splenocytes from BALB/c mice together with plate bound α-CD3 and α-CD28 antibodies." (PMID 36121874, 2022).
colorectal cancer (17 papers, 2012 to 2025). A primary or metastatic malignant neoplasm that affects the colon or rectum. "Functional polymorphisms identified in the 3′-UTR of B7/CD28 genes dysregulate the miR-3692-3p/B7/CD28 axis in colorectal cancer." (PMID 34680382, 2021). "Recently, the association between CD28 rs3116496 polymorphism and cancer risk has been widely investigated, such as cervical cancer, non-small-cell lung cancer, colorectal cancer, BC, and renal cell carcinoma." (PMID 29089469, 2017). "Here, we investigated the metabolism, ALs, cytotoxicity, and immunoregulatory functions of CD64/CD28/CD3ζ in colorectal cancer (CRC) and squamous cell carcinoma of the head and neck." (PMID 39962623, 2025). "Downregulated CD28+ T cells have been observed in colorectal cancer, effectively crippling antitumor immune surveillance by disrupting CD8+ T cell activation." (PMID 41427020, 2025). "For instance, miR-424 carried by colorectal cancer (CRC)-derived EVs downregulates the expression of CD28 in T cells, thereby attenuating the CD28-CD80/86 costimulatory pathway and inhibiting T cell activation to facilitate immune evasion." (PMID 40908470, 2025). "Here, we compared the hinge and transmembrane domains derived from either the CD8ɑ or CD28 molecule in identical GUCY2C-targeted third-generation designs for colorectal cancer." (PMID 39315411, 2024). "Recent studies have demonstrated that a significantly lower level of CD28 surface expression on T cells was detected in diabetic rats, children with T1D, cell leukaemia, chronic lymphocytic leukaemia and colorectal cancer." (PMID 25009576, 2014). "Colorectal carcinoma cells were coincubated with engineered autologous CIK cells with the CD3ζ or the combined CD28-CD3ζ CAR." (PMID 22481963, 2012). "Decreased CD28 expression has been observed in some types of cancer, for example, in the dysfunctional peripheral T-lymphocytes from patients with hairy cell leukemia and chronic lymphocytic leukemia, as well as in colorectal cancer patients." (PMID 26918337, 2016). "CD8+ T cells were first stimulated with magnetic αCD3/CD28 beads and IL2 to become CTLs and then coincubated with murine colorectal cancer cell lines (CT26 or MC38)." (PMID 39292167, 2024). "Taken together activation of CIK cells from colorectal cancer patients toward autologous tumour cells can be improved by CAR engagement of target cells and is furthermore increased by combined CD28-CD3ζ CAR signaling." (PMID 22481963, 2012). "Although miRNAs have been increasingly described to be involved in the inhibition of B7/CD28 molecules, further investigations are needed to fully understand whether they participate in TGF-β1-mediated regulation of B7/CD28 molecules in colorectal cancer." (PMID 27626488, 2016).
multiple sclerosis (17 papers, 2009 to 2024). A progressive autoimmune disorder affecting the central nervous system resulting in demyelination. "In multiple sclerosis, miR-193a was strongly upregulated in CD4+ lymphocytes in response to CD3/CD28 stimulation, suggesting miRNA-dependent regulatory involvement in immune function." (PMID 33535558, 2021). "CD28 (60–80% CD3+) were found lower in vascular dementia and Parkinson's disease with regard to controls, anxiety, depression, psychosis, migraine, epilepsy, multiple sclerosis, and posttraumatic brain injury." (PMID 27190492, 2016).
Obesity (17 papers, 2015 to 2024). Accumulation of substantial excess body fat. "Specifically, loci associated with T cell activation (CD3, CD28) were hypomethylated in cord blood CD4 T cells from babies born to mothers with obesity." (PMID 33912153, 2021). "We found that younger patients with class 4 obesity had higher blood levels of CD8+CD28- T lymphocytes (cytotoxic effector T lymphocytes)." (PMID 37334132, 2023). "To further investigate the relationship of obesity with the immunophenotype of T cells in participants with T2D, we analyzed the CD28 − CD57+ senescent subset of the CD4+ and CD8 + T cells using flow cytometry." (PMID 37735474, 2023). "In another study, obesity was associated with a decreased number of activated CD8+ T cells expressing CD28, CD40 ligand (CD40L), IFNγ as well as both IFNγ and GrB, and both CD28 and interleukin 12 receptor (IL12R)." (PMID 36295052, 2022). "As well, both obesity and aging are associated with a marked increase in the CD4/CD8 T cell ratio and higher T cell IFNγ production in response to anti-CD3 plus anti-CD28 stimulation." (PMID 32027700, 2020). "Ex vivo ligation of CD3/CD28 for 72 h revealed the presence of granzyme B–producing CD8 + T cells in lean AT, and interestingly, obesity induced a fourfold increase in the proportion of these cells." (PMID 32973799, 2020). "In the class 4 obesity group, we found positive correlations between the absolute number of CD4+CD45RO+ T lymphocytes and TBF, and a negative association between the absolute number of CD8+CD28- lymphocytes and age." (PMID 37334132, 2023). "In response to CD3/CD28 stimulation, the secretion of TNF-α by CD8+ T cells trended towards positive correlation with BMI while IFN-γ secretion by CD8+ T cells significantly negatively correlated with BMI in young patients, suggesting an impairment of CD8+ T cells antiviral with obesity." (PMID 34707619, 2021). "Here, ASCs were obtained from 2 groups, donors with T2D and obesity (dASCs) or nondiabetic donors with normal-weight (ndASCs), and then cultured with anti-CD3/CD28-stimulated allogeneic CD4 T cells." (PMID 36945068, 2023). "In addition, no impairment of CD28, ICAM-1 (CD54) or CCR5 expression was observed, suggesting obesity does not impair the expression of these key receptors involved in Vγ9Vδ2 T cell co-stimulation or homing." (PMID 25785862, 2015).
prostate carcinoma (17 papers, 2011 to 2025). A carcinoma that arises from epithelial cells of the prostate gland. "High serum levels of CD28, among other immune checkpoint proteins, have been associated with worse prognosis in prostate cancer." (PMID 36835246, 2023). "CD28 is also associated with the prognosis of patients with prostate cancer." (PMID 34852825, 2021). "NK-92 cells expressing a first-generation EpCAM-specific CAR or coexpressing IL-15 and a second-generation EpCAM-specific CAR with intracellular signaling domains of CD28 were also developed to treat prostate cancer in mouse models." (PMID 30410941, 2018). "T cells expressing second-generation EpCAM-specific CARs with the intracellular signaling domain of CD28 were reported to treat prostate cancers in mouse models." (PMID 30410941, 2018). "Resveratrol induces growth arrest through activation of FOXO transcription factors in prostate cancer cells and suppresses the immune response through CD28/CTLA-4 and CD80 co-stimulatory pathways." (PMID 25501752, 2014). "Here, we examined the expression of B7-H3 in prostate cancer tissues and cells and developed a second-generation CAR that specifically targets B7-H3 and CD28 as costimulatory receptor to explore its tumoricidal potential against prostate cancer in vitro and in vivo." (PMID 37149721, 2023). "We synthesized the B7-H3 scFv sequence based on 8H9 clone and constructed the second-generation B7-H3 CAR containing CD8α transmembrane region, CD28 intracellular costimulatory domain, and CD3ζ intracellular signaling domain after confirming that B7-H3 is highly expressed in prostate cancer." (PMID 37149721, 2023). "28ζ CAR bearing this modification outperformed BBζ CAR against prostate cancer, suggesting that excessive CD28-derived proximal signaling limited CAR T cell persistence, but adequate CD28 signaling could be a better option compared to 4-1BB in specific cases." (PMID 36498890, 2022). "Another study comparing 4-1BB and CD28 signaling in a PSCA CAR to treat patient derived prostate cancer xenografts found 4-1BB to be superior to CD28, with 4-1BBζ CARs leading to less exhaustion and better antigen selectivity (however, in vitro killing was equal between the two CARs)." (PMID 30804938, 2019). "In a large series of patients with various types of malignancies suppressive IL-10-producing CD8+CD28 cells could be isolated and cells from prostate cancer patients expressing CD28, CD25 and FOXP3+ suppressed T cells in a contact-dependent fashion." (PMID 24212779, 2011). "Soluble T cell regulatory proteins CD28, CD80, CTLA4, and HVEM were correlated with both biochemical recurrence and progression risks in prostate cancer." (PMID 40659985, 2025). "Mouse prostate cancer cells (RM-1) were irradiated (20 Gy) and co-cultured with mouse splenocytes stimulated with anti-CD3/CD28 antibodies." (PMID 36229853, 2022).
cervical cancer (16 papers, 2012 to 2025). A primary or metastatic malignant neoplasm involving the cervix. "Compared to PD-1/ICOS and PD-1/CD28, PD-1/4-1BB demonstrated a closer association with cervical cancer." (PMID 38756662, 2024). "The expression of BTLA, KLRK1, CD80, and CD28 reduced the risk score, and these were suggested as protective factors in cervical cancer prognosis." (PMID 39312339, 2024). "The synergistic stimulation factor of CD28 which maintains immune homeostasis plays a role in increasing susceptibility to cervical cancer." (PMID 24992025, 2014). "Polymorphism genes such as CD28 (rs3116496), IFNG (rs2430561), Pre-miR (rs11134527), and LAMB3 (rs2566), along with DNA-repairing SNPs, affect individual susceptibility to cervical cancer." (PMID 40649795, 2025). "The co-expression levels of PD-1/4-1BB, PD-1/ICOS, and PD-1/CD28 on CD8+ tumor-infiltrating lymphocytes (TILs) were significantly higher in cervical cancer patients compared to those in peripheral blood." (PMID 38756662, 2024). "PD-1/4-1BB, PD-1/ICOS, and PD-1/CD28 exhibit elevated co-expression on CD8+TILs of cervical cancer, while demonstrating lower expression in circulating T cells." (PMID 38756662, 2024). "The expression of CD28 and FOXP3 was highly correlated, and high expression of IDO1, FOXP3, CD28, and FOXP3 was all associated with improved survival in cervical cancer." (PMID 39672307, 2024). "Here, we comprehensively analyzed the co-expression of 4-1BB, ICOS, CD28 with PD-1 on CD8+ T lymphocytes, focusing on the more closely associated PD-1 + 4-1BB co-expression in cervical cancer." (PMID 38756662, 2024). "Recent work demonstrated that CD28 contributes to the development of cervical cancer and can serve as a prognostic marker for cervical cancer." (PMID 37735483, 2023). "Particularly, patients with advanced cervical cancer have exhibited a markedly reduced proportion of CD28+ cells within both CD4+ and CD8+ T cell subpopulations." (PMID 26486970, 2015). "TISIDB was employed to examine immune infiltration in cervical cancer, revealing that IDO1 levels exhibit a significantly positive association with ICOS, C10orf54, CD27, CD28, CD70, and other immunostimulatory factors, which negatively regulate the expression of CD276." (PMID 39312339, 2024). "Also, gene-gene interaction between CD28 and IFNG could increase females’ susceptibility to cervical cancer." (PMID 33160404, 2020). "Our study reveals that the co-expression frequencies of PD-1/4-1BB, PD-1/ICOS, and PD-1/CD28 on CD8+TILs (capable of specifically recognizing and killing tumor cells) from cervical cancer are higher than those in PBMCs." (PMID 38756662, 2024). "By testing 11 cervical cancer tissue and 11 adjacent normal tissues specimens using TMA, CD80 and CD28 expression are lower in cervical squamous cell carcinoma tissues." (PMID 34852825, 2021). "Secondly, we identify CD40, CD27, and TIM-3 to specifically discriminate cervical cancer from other groups and CD40, CD28, and TLR2 to positively correlate to genital inflammation." (PMID 32802959, 2020). "We identified 79 prognostic TIME-related genes in cervical cancer and validated 4 genes (CCR7, CD28, PD-1, and ZAP70)." (PMID 32733542, 2020). "Increased CD28 expression has been shown to correlate with improved survival in head and neck squamous cell carcinoma (HNSCC), while increased FLT3LG expression has previously been shown to correlate with improved survival in cervical cancer." (PMID 39672307, 2024). "However, there is limited knowledge regarding the co-expression patterns of 4-1BB, ICOS, CD28, with PD-1 on CD8+T lymphocytes, along with their immunological and clinical significance in patients with cervical cancer." (PMID 38756662, 2024). "Taken together, our results reveal the existence of two separate CD4+NKG2D+ T cell subsets defined by the co-expression or absence of CD28, the latter more likely to be present in anti-inflammatory environments and in patients with cervical cancer." (PMID 26486970, 2015).